CBLN1 (cerebellin 1 precursor)
Description:
Required for synapse integrity and synaptic plasticity. During cerebellar synapse formation, essential for the matching and maintenance of pre- and post-synaptic elements at parallel fiber-Purkinje cell synapses, the establishment of the proper pattern of climbing fiber-Purkinje cell innervation, and induction of long-term depression at parallel fiber-Purkinje cell synapses. Plays a role as a synaptic organizer that acts bidirectionally on both pre- and post-synaptic components. On the one hand induces accumulation of synaptic vesicles in the pre-synaptic part by binding with NRXN1 and in other hand induces clustering of GRID2 and its associated proteins at the post-synaptic site through association of GRID2. NRXN1-CBLN1-GRID2 complex directly induces parallel fiber protrusions that encapsulate spines of Purkinje cells leading to accumulation of GRID2 and synaptic vesicles. Required for CBLN3 export from the endoplasmic reticulum and secretion (By similarity). NRXN1-CBLN1-GRID2 complex mediates the D-Serine-dependent long term depression signals and AMPA receptor endocytosis. Essential for long-term maintenance but not establishment of excitatory synapses (By similarity). Inhibits the formation and function of inhibitory GABAergic synapses in cerebellar Purkinje cells (By similarity). The cerebellin peptide exerts neuromodulatory functions. Directly stimulates norepinephrine release via the adenylate cyclase/PKA-dependent signaling pathway; and indirectly enhances adrenocortical secretion in vivo, through a paracrine mechanism involving medullary catecholamine release (By similarity).
Tractability: Antibody: UniProt places it where antibodies can reach, with medium confidence; UniProt predicts a signal peptide or a membrane-spanning region; its Gene Ontology location is reachable by antibodies, with medium confidence.
Gene: Protein-coding gene on chromosome 16 (49,277,917 to 49,281,838, reverse strand). Ensembl gene ENSG00000102924.
Subcellular location: Secreted; Postsynaptic cell membrane
Subcellular location (Human Protein Atlas): Cytosol; Flagellar centriole; Mid piece; Principal piece; Calyx; Perinuclear theca; Predicted to be secreted
Gene Ontology:
Molecular function: protein binding; signaling receptor regulator activity; identical protein binding
Biological process: negative regulation of excitatory postsynaptic potential; positive regulation of long-term synaptic depression; trans-synaptic signaling by trans-synaptic complex, modulating synaptic transmission; cerebellar granule cell differentiation; chemical synaptic transmission; heterophilic cell-cell adhesion; maintenance of synapse structure; negative regulation of inhibitory synapse assembly; nervous system development; synapse organization; trans-synaptic signaling, modulating synaptic transmission; regulation of postsynaptic density assembly; regulation of presynapse assembly
Cellular component: extracellular matrix; synapse; trans-synaptic protein complex; extracellular region; glutamatergic synapse; postsynaptic membrane; synaptic cleft; parallel fiber to Purkinje cell synapse
Genetic constraint (gnomAD): Loss-of-function variants: 5 observed, 15.12 expected, observed/expected ratio (o/e) 0.33, 90% interval 0.17 to 0.69. The upper end of that interval is the gene's LOEUF score, 0.69, which puts it in group 2 of 6, group 1 being the genes least tolerant of losing a copy. Missense variants: 164 observed, 261.71 expected, observed/expected ratio (o/e) 0.63, 90% interval 0.55 to 0.71. Synonymous variants: 90 observed, 108.72 expected, observed/expected ratio (o/e) 0.83, 90% interval 0.7 to 0.99.
Homologues: Orthologues: chimpanzee CBLN1 (100% identical), dog CBLN1 (99% identical), rat Cbln1 (99% identical), mouse Cbln1 (99% identical), pig CBLN1 (99% identical), macaque CBLN1 (98% identical), tropical clawed frog cbln1 (88% identical), zebrafish cbln1 (87% identical), rabbit CBLN1 (73% identical), guinea pig CBLN1 (54% identical). Paralogues in human: CBLN2 (76% identical), CBLN4 (69% identical), CBLN3 (56% identical).
Diseases named in the same sentence as CBLN1 in open-access papers:
CBLN1 is named in the same sentence as 36 diseases in open-access papers, as found by Europe PMC text mining. Sharing a sentence is not in itself a finding about the gene and the disease. The quoted sentences say what the papers report.
Ataxia (6 papers, 2018 to 2025). Ataxia refers to impaired coordination of voluntary muscle movement. "Administration of recombinant Cbln1 induced new PF-PC synapses in vitro, transiently restoring PF-PC synapses in vivo, and completely rescued severe ataxia in Cbln1 mutant mice." (PMID 40016581, 2025). "Cbln1−/− mice showed cerebellar ataxia and impaired performance accompanied by a significant reduction in the number of PF-PC synapses, as well as severe impairment to synaptic function." (PMID 33762741, 2021). "Cerebellin-1 (Cbln1) is an ECM glycoprotein involved in cell adhesion that may play a role in cerebellar ataxia." (PMID 37108212, 2023). "Our method could also be easily employed with animal models of cerebellar defects and diseases, such as Cbln1-null mice, En2-null mice, and cerebellar ataxia mice, and allow for the fast screening of interventions or drug treatments in these disease models." (PMID 35741428, 2022).
autism (4 papers, 2017 to 2022). Persistent deficits in social interaction and communication and interaction as well as a markedly restricted repertoire of activity and interest as well as repetitive patterns of behavior. "In this context, several genes downregulated in the brainstem of Hoxa5 cKO mouse at P21, such as Grm4, Cbln1, En2, Camk4, and Cadps2, have been associated to autism traits either in humans or in mouse models." (PMID 29187810, 2017). "Thus, while the focus for CBLN1 has been central, it remains an interesting possibility that autism-linked CBLN1 deficits also impair sociability by altering sensation of socially relevant tactile stimuli by its function in a subset of C-LTMRs." (PMID 31807945, 2019).
Anxiety (3 papers, 2019 to 2025). Intense feelings of nervousness, tension, or panic often arise in response to interpersonal stresses. "Moreover, at the behavioral level, loss of Cbln1 has been associated with impairments in fear memory and spatial learning, while loss of Baiap3 is implicated in the development of anxiety and depression." (PMID 40606839, 2025). "Furthermore, GluD1 KO and Cbln1 KO mice display impaired fear acquisition and altered anxiety-like behaviors, which are amygdala-dependent behaviors." (PMID 34685624, 2021). "Furthermore, injection of recombinant Cbln1 into the right CeA was effective in mitigating pain-related audible and ultrasonic vocalizations, mechanical hypersensitivity and anxiety-like behavior in a neuropathic pain model." (PMID 34685624, 2021).
autism spectrum disorder (2 papers, 2018 to 2020). A spectrum of developmental disorders that includes autism, and Asperger syndrome. "In addition, downregulation of Cbln1 mRNA was observed in mice carrying a triple dose of Ube3a, a model mouse for autism spectrum disorder." (PMID 32078638, 2020).
Gait ataxia (2 papers, 2018 to 2023). A type of ataxia characterized by the impairment of the ability to coordinate the movements required for normal walking. "In the present study, we found a transient improvement in gait ataxia by an injection of the Cbln1 protein; our previous study showed multiple CF innervations were still present after Cbln1 treatment." (PMID 29670152, 2018). "Therefore, there is a possibility that the injected Cbln1 may not have diffused sufficiently through the intermediate cerebellum to improve gait ataxia." (PMID 29670152, 2018).
atherosclerosis (1 paper, 2023). A disease characterized by the build-up of fatty material and calcium deposition in the arterial wall resulting in partial or complete occlusion of the arterial lumen. "Two BCAA-raising genes (MRL33 and CBLN1) were preferentially associated with myocardial infarction risk in the presence of atherosclerosis (p < 0.003)." (PMID 36984843, 2023).
epilepsy (1 paper, 2020). A brain disorder characterized by episodes of abnormally increased neuronal discharge resulting in transient episodes of sensory or motor neurological dysfunction, or psychic dysfunction. "Thus, L2–3_Cux2 and L5–6_Fezf2 subtypes co-clustered with Sst_Tac1 and Vip_Cbln1 subtypes, whereas L3_Cux2_Prss12 co-clustered with Pvalb_Sulf1, which might underlie local neuronal networks with most strongly affected in the epilepsy transcriptome." (PMID 33028830, 2020).
glioblastoma (1 paper, 2022). The most malignant astrocytic tumor (WHO grade IV). "The four tumor-related genes (TNFAIP6, C15orf48, WSCD2, and CBLN1) were neither reported in ferroptosis-related reports nor in glioblastoma-related studies, which were first found by us." (PMID 35720126, 2022).
Hypertension (1 paper, 2023). The presence of chronic increased pressure in the systemic arterial system. "CBLN1 is a novel appetite-stimulating peptide related to renin expression that may be mediated by hypothalamic neuropeptide, which is a sympathetic neurotransmitter related to hypertension and a variety of CVDs." (PMID 36984843, 2023).
neuroendocrine disorder (1 paper, 2023). A disease or disorder that affects the neuroendocrine gland, any of the organized aggregations of cells that function as secretory or excretory organs and that release hormones in response to neural stimuli. "Overall, the causal effect may involve two pathophysiological pathways, including glucose metabolism (PPM1K and TRMT61A) related to plaque progression and the newly discovered neuroendocrine disorders (CBLN1, MRPL33, and C2orf16) related to plaque rupture and thrombosis." (PMID 36984843, 2023).
neuropathic pain (1 paper, 2021). Chronic pain caused by damage to nerve fibers. "Thus, Cbln1 mitigates both sensory and averse-affective behaviors in a neuropathic pain condition." (PMID 34685624, 2021).
Pain (1 paper, 2021). An unpleasant sensory and emotional experience associated with actual or potential tissue damage, or described in terms of such damage. "In inflammatory and neuropathic pain models, GluD1 and its partner cerebellin 1 (Cbln1) are downregulated while AMPA receptor is upregulated." (PMID 34685624, 2021). "We further examined the effect of recombinant Cbln1 in the SNL model of chronic neuropathic pain." (PMID 34685624, 2021).
type 2 diabetes (1 paper, 2016). "There was an association of the isoleucine-raising allele of rs1420601 near CBLN1 with higher BMI, but this did not affect the main analysis results (OR for type 2 diabetes after exclusion of rs1420601 = 1.50, 95% CI 1.25–1.80, p = 0.000013)." (PMID 27898682, 2016).
tumor (4 papers, 2018 to 2025). "However, little is known about the function of CBLN1 and TBX18 in tumorigenesis and the progression of tumor." (PMID 32441304, 2020).
cancer (1 paper, 2025). A tumor composed of atypical neoplastic, often pleomorphic cells that invade other tissues. "CBLN1, typically associated with synaptic function, has limited data linking it to cancer, though recent studies suggest it may influence cell signaling in specific malignancies." (PMID 40567599, 2025).
CBLN1 also shares sentences with these, for which no sentence is quoted: cerebellar ataxia (3 papers); breast carcinoma (1); Cognitive impairment (1); colorectal cancer (1); COVID-19 (1); depression (1); epilepsy syndrome (1); focal epilepsy (1); gastric cancer (1); glucose metabolism disorder (1); infection (1); leiomyoma (1); lung carcinoma (1); macular degeneration (1); memory impairment (1); myocardial infarction (1); neurological disorders (1); Obesity (1); psychiatric disorder (1); Stroke (1); temporal lobe epilepsy (1).